IDO1 (indoleamine 2,3-dioxygenase 1)
Diseases named in the same sentence as IDO1 in open-access papers (continued):
Sharing a sentence is not in itself a finding about the gene and the disease.
cancer (continued). "Moreover, the PET signals in the MLNs closely correlated with therapeutic efficacy, implying that the IDO1 status in the MLNs is an unprecedented surrogate marker of the cancer-immune set point for combinatorial immunotherapies." (PMID 34148865, 2021). "However, IDO1 pathway remains a relevant target to block in order to improve the efficacy of cancer immunotherapy." (PMID 34073463, 2021). "Finally, the protocol has been successfully applied for IDO1 activity determination to show changes in enzyme activity depending on cancer cell type and treatment." (PMID 33541164, 2021). "These luminal B cancers exhibited higher activity of pathways associated with the ECM-regulated Hippo pathway and immune tolerance, including mRNAs encoding checkpoint inhibitor molecules (IDO1, PD1, LAG3) and increased IFNγ-STAT1 signaling." (PMID 34359625, 2021). "That makes AGEs and IDO1 the important players in the cancer microenvironment." (PMID 33541164, 2021). "Importantly, the described protocol was applied for IDO1 enzymatic activity estimation in two different human cancer cells (ovarian: SK-OV-3 and breast: MDA-MB-231)." (PMID 33541164, 2021). "Although much less studied, the IDO1 paralog IDO2 may represent a valid alternative as drug target in cancer immunotherapy." (PMID 33968089, 2021). "In addition, IDO1 exhibits great prognostic and clinicopathological significance for patients with cancer." (PMID 34631703, 2021). "However, recent failures of phase III clinical trials with IDO1 inhibitors involved in cancer immunotherapies highlight the urgent need to develop appropriate methods for tracking IDO1 when the cancer-immune milieu is therapeutically modified." (PMID 34148865, 2021). "Indoleamine 2,3-dioxygenase 1 (IDO1) has emerged as an attractive target for cancer immunotherapy." (PMID 31991635, 2020). "Thus, we have demonstrated that the well-described role played by the KP in mediating cancer immune tolerance extends beyond IDO1, potentially identifying KMO and KYNU inhibitors as new therapeutic BrCa targets." (PMID 33109232, 2020). "IDO1 inhibitors have been tested in a variety of anti-cancer treatments, including epacadostat, indoximod, and navoximod, but compared with the results of preclinical trials, the efficacy of IDO1 inhibitors alone have not been objectively reflected in the clinical trials." (PMID 33511116, 2020). "Considering the success of this screening strategy, the inclusion of KP profile screening of cancer patients may improve treatment efficacy in future trials of IDO1 inhibitors." (PMID 33109232, 2020). "In this way, IDO1 enzyme suppresses the immune response against cancer cells." (PMID 32090113, 2020). "Furthermore, induction of type I IFN signaling post-IR has been shown to increase expression of the immunosuppressive indoleamine 2,3 dioxygenase 1 (IDO1) protein in cancer cells." (PMID 33238631, 2020). "Emerging studies have shown that IDO1 was expressed in a large number of human cancers." (PMID 33062039, 2020). "The IDO1 enzyme is activated in many human cancers including NMIBC." (PMID 33585182, 2020). "Additionally, our study is not the only one to report a favourable prognostic impact of IDO1 expression in cancer cells." (PMID 32227579, 2020). "As shown in previous studies, IDO1 inhibitors could enhance the antitumor efficacy of chemotherapy regimen and the combination therapy of IDO1 inhibitor and chemotherapy might be a feasible therapeutic strategy in malignant tumor." (PMID 32733806, 2020). "PD‐L1 and LAG3 can be induced by IFN‐γ, the same as IDO1, and this may partially explain their positive correlation in cancer samples." (PMID 32227579, 2020). "However, one of these drugs (epacadostat) recently showed poor efficacy in clinical trials on cancer patients and, as a consequence of this failure, other clinical trials with IDO1 inhibitors have been suspended, canceled, or downsized." (PMID 33584695, 2020).
cancer (continued). "Indoleamine 2,3-dioxygenase 1 (IDO1) is a heme-containing intracellular enzyme that catalyzes the first and rate-determining step of tryptophan metabolism and is an important immunotherapeutic target for the treatment of cancer." (PMID 32210078, 2020). "In cancer, aberrant activation of IDO1 results in suppression of antitumour immunity." (PMID 32466694, 2020). "Therefore, gut microbiota-induced IFN-γ probably increases cancer pathogenesis through modification of the kynurenine pathway at IDO1 step (see Section “Kynurenine Pathway”)." (PMID 33330446, 2020). "Blocking this immunosuppressive effect of IDO1 was thought to improve outcomes in cancer patients." (PMID 32090113, 2020). "Therefore, IDO1 inhibitors once attracted considerable attention as potential agents for cancer treatment." (PMID 33101032, 2020). "As the kynurenine, which is degraded from tryptophan by IDO1 enzyme activity and downstream derivative metabolites of kynurenine plays, an important role in immune suppression, multiple types of IDO1 inhibitors are developed for cancer treatments." (PMID 32933162, 2020). "In this context, IDO1 inhibitors are promising in the new generation of immunotherapy for cancer." (PMID 32907554, 2020). "It is possible to speculate that in these cancers the expression of IDO1 and the synthesis of kynurenine might contribute to activate the receptor." (PMID 31936153, 2020). "IDO1 has predictive value in some tumors and can be used to stratify and define some cancers." (PMID 32000802, 2020). "Indoleamine 2, 3-dioxygenase 1 (IDO1), a potent immunosuppressive molecule, has been strongly associated with T-cell infiltration, but it lacks universal prognostic significance among all of the cancer subtypes." (PMID 33425745, 2020). "The level of IDO1 expression has been shown to predict poor outcomes in these cancers." (PMID 31124055, 2020). "However, preclinical studies have shown that IDO1 inhibitors are ineffective as stand-alone cancer treatments." (PMID 31124055, 2020). "Indeed, IDO1 was found to be one of the immune checkpoint proteins involved in cancer immune escape." (PMID 33304345, 2020). "In conclusion, the involvement of IDO1 in different cancers appears to be highly complex." (PMID 32227579, 2020). "However, immune-competent subtypes in several cancer types had relatively lower expressions than immune-deficient subtypes, particularly VTCN1 in GBM and LAG3 and IDO1 in PCPG were significantly elevated in immune-deficient subtypes." (PMID 32533054, 2020). "Hence, these findings have motivated interest in developing IDO1 inhibitors for cancer immunotherapy." (PMID 32466694, 2020). "TDO2is also expressed in many cancers, but at lower levels than IDO1, except inhepatocellular carcinoma, where expression is considerably higher among alltissues examined and relative to that of IDO1." (PMID 31105983, 2019). "Besides its role in immunosuppression, IDO1 promotes cancer development by inducing inflammatory neovascularization, interacting with checkpoint inhibitors, and modulating gut microbiota." (PMID 31316514, 2019). "As the dominant viewpoint of the medical field, IDO1 is an important target for cancer drug development, but its inhibitory mechanism remains unknown." (PMID 32047753, 2019). "For instance, Indoleamine 2,3-dioxygenase 1 (IDO-1) which catalyzes the decomposition of tryptophan into kynurenic acid, may prevent CTLs from attacking cancer cells while upregulating Treg immunosuppression." (PMID 31014381, 2019). "Accordingly, inhibition of IDO-1 would be a very useful strategy for the treatment of cancer." (PMID 30889860, 2019). "In humans, IDO1 is reported to be highly expressed in a wide range of cancers." (PMID 31391111, 2019). "Recently, IDO1 is becoming a focus in the area of cancer therapy." (PMID 31315643, 2019). "LBJ-10 can serve as ideal leads for further modifications as IDO1 inhibitors for cancer treatment." (PMID 30734612, 2019).
cancer (continued). "Our results also support that IDO1-mediated immunosuppression may be partly due to increased extracellular collagen matrix surrounding cancer cells." (PMID 31315643, 2019). "However, the expression of IDO1 is significantly higher in cancer cells treated with IFN-γ than in untreated cells." (PMID 31391111, 2019). "Therefore, these molecules should be further investigated due to their IDO1 inhibitor ability and their potential use in cancer immunotherapy." (PMID 31423846, 2019). "Thus, H2S, as a novel negative regulator of IDO1, shows encouraging antitumor immunotherapeutic effects and represents a novel therapeutic target in cancer therapy." (PMID 30777103, 2019). "It has been shown that down-regulating one of the key driver of polyamine metabolism, IDO1, could improve the response rate of immunotherapy in cancer." (PMID 31417867, 2019). "In addition, the ligation of CTLA-4 with the B7 family co-stimulatory molecules of CD80 and CD86 induces IDO1 expression in DCs; therefore, IDO1 is an important immunotherapy target in cancer treatment." (PMID 30658461, 2019). "Several studies have already revealed that IDO1 expression in a large number of cancers could lead to the depletion of TRP and accumulation of NRK and KYN, which inactivates T effector cells and thus suppresses immunity." (PMID 31805976, 2019). "IDO1 inhibition has been anactive targeting area for cancer therapy." (PMID 31105983, 2019). "In addition, IDO-1 inhibitors have demonstrated a significant cooperative effect with chemotherapy, radiotherapy, or cancer vaccines in preclinical models of cancer." (PMID 30889860, 2019). "Notably, IDO1 inhibitors are under development as a cancer treatment, raising the possibility of re-purposing." (PMID 31186442, 2019). "IDO1 inhibitors are undergoing clinical trials for cancer therapy." (PMID 31324754, 2019). "Several small molecule-based IDO1 inhibitors in combination with immune checkpoint inhibitors are currently being evaluated in various stages of clinical trials for the treatment of different types of cancers and other diseases." (PMID 31804586, 2019). "All this evidence confirms that IDO1 inhibition might enhance the efficacy of pharmacological cancer therapy and is a potential breakthrough approach to cancer therapy." (PMID 30734612, 2019). "Moreover, human cancers often express high levels of indoleamine-2,3-dioxygenase 1 (IDO1) and/or TDO2, the initial Trp-catabolic enzymes of the KP." (PMID 31866995, 2019). "Interestingly, cancer cells displayed an up-regulation of either TDO2 or AFMID (the expression of IDO1 was extremely low in our samples)." (PMID 31416966, 2019). "MGC-803, HGC-27 and NCI-N87 cancer cell lines revealed lower expression level of IDO1." (PMID 31315643, 2019). "Successful use of immune checkpoint inhibitors and recent clinical developments of the inhibitors of the IDO1 enzyme instigate scientists to develop potent small molecule-based IDO1 inhibitors that will adequately address this cancer immunotherapeutic approach." (PMID 31804586, 2019). "We analyzed the effects of IDO1 metabolite L-kynurenine on cancer cells." (PMID 31315643, 2019). "Overall, these findings suggest that suitably substituted 4,5-disubstituted 1,2,3-triazole derivatives are potent inhibitors of IDO1 enzyme and could be of interest as drug targets in cancer and other life-threatening diseases." (PMID 31804586, 2019). "IDO1 linking the process of immune evasion by tumors represents a novel target for cancer therapy." (PMID 29932010, 2018). "Indoleamine-2,3-dioxygenase 1 (IDO1) is a monomeric 45 kDa hemoglobin-containing oxidase, it is one key dioxygenase in the process of tryptophan-kynurenine metabolism, and usually acts as one immune escape strategy for cancer cells." (PMID 29974338, 2018).
cancer (continued). "For example, a recent Phase 1/2 study that assessed the effect of IDO1 inhibition in combination with a DC vaccine showed a good therapy tolerance and suggested a possible chemo-sensitization effect in patients with advanced cancers." (PMID 30076128, 2018). "Thus, IDO1 acts as a direct guard against T-cell attacking and overexpressed in many human cancer types, including breast cancer, prostate cancer, lung cancer, and colon cancer." (PMID 29651242, 2018). "Tryptophan catabolites produced by microbiota such as gut Lactobacillus can also act as AHR ligands, confounding a clear interpretation of the link between IDO1 and cancer that may involve microbiota-mediated tryptophan catabolism." (PMID 30254983, 2018). "However, with the discovery of IDO1-mediated immunosuppressive functions, the pro-cancer activity of the enzyme has been recognized." (PMID 29445380, 2018). "Indoleamine 2,3-dioxygenase 1 (IDO1) activity links to immune escape of cancers." (PMID 29932010, 2018). "Therefore, inhibition of IDO1 activity by small-molecule drug was one valuable strategy for cancer patient to re-establish immunogenic response." (PMID 29974338, 2018). "Indeed, other evidence has been presented for an autocrine feedback pathway involving IDO1, AHR, and IL-6 that controls IDO1 expression in cancer cells." (PMID 30254983, 2018). "Mechanisms whereby cancer cells overcome IDO1-mediated tryptophan deprivation are of intense interest and scientific speculation." (PMID 30466445, 2018). "Furthermore, IDO1 is involved in the formation of resistance to immune checkpoint inhibitors, and the combination of an IDO1 inhibitor with checkpoint inhibitors represents an alternative strategy in cancer immunotherapy." (PMID 30068361, 2018). "Most cancer types have high IDO1 expression, which is correlated with poor survival and prognosis." (PMID 30068361, 2018). "In addition to cancer, IDO1 plays role in autoimmune disorders, immunosuppression and chronic infection." (PMID 30112109, 2018). "In vivo studies using animal models of human cancers treated with IDO1 inhibitors demonstrated that IDO1 may be a potential therapeutic target for the cancer immunotherapy." (PMID 29651242, 2018). "Acting in such a way, IDO1 contributes to the escape of cancer from the immunosurveillance." (PMID 30150994, 2018). "Besides its role in immunosuppression, IDO1 also contributes to cancer development by promoting inflammatory neovascularization, interacting with checkpoint inhibitors, and modulating gut microbiota." (PMID 30068361, 2018). "Combination of IFN-γ treatment with IDO1 inhibitors is a promising new cancer immunotherapeutic strategy that effectively enhances antitumor immunity and eliminates TRCs (i.e., stem cell-like cancer cells that are self-renewing, highly tumorigenic, and can repopulate tumors)." (PMID 29445380, 2018). "Ras and Kit also upregulate IDO1 expression in cancer cells." (PMID 30068361, 2018). "Inhibition of IDO1 provides a new approach for cancer treatment." (PMID 29932010, 2018). "Overexpression of IDO1 acts as the guard of T-cell attacking for many cancer types." (PMID 29651242, 2018). "IDO1 appears to be chronically activated in cancer patients." (PMID 29468141, 2018). "In addition, based on their immunosuppressive functions, IDO1 is becoming a potential target for drug discovery in cancer immunotherapy." (PMID 29304754, 2018). "IDO1 was found to be overexpressed widely in human cancers and 1MT could slow the growth of murine tumors." (PMID 30254983, 2018). "Accordingly, two of the three ways by which IDO1 is supposed to suppress T-cell-mediated immune response may not take place if enough free fatty acids are present in the cancer microenvironment." (PMID 30150994, 2018).
cancer (continued). "Indoleamine-2,3-dioxygenase 1 overexpression increases the relative concentration of Kyn compared to Trp, hence Kyn/Trp ratio can be used as a prognostic clinico-pathological marker to monitor cancer invasiveness and progression." (PMID 29445380, 2018). "Flow cytometry analyses validated IDO1 upregulation in these cancer cell lines." (PMID 29685162, 2018). "As of July 2018, there were ~1,500 publications on IDO1 and cancer in PubMed." (PMID 30400835, 2018). "Human indoleamine 2,3-dioxygenase 1 (hIDO1) is an immunotherapeutic target for cancer therapy." (PMID 29167421, 2017). "Interferon-γ (IFNγ) has been shown to induce IDO1 in a variety of malignancies." (PMID 29156701, 2017). "Nevertheless, several IDO1 inhibitors including indoximod and epacadostat are now undergoing Phase I/II clinical trials in cancer patients in whom induction of IDO and resulting evasion of anti-tumoral immune responses may play a role." (PMID 28066416, 2016). "Based on these observations, IDO1 small molecule antagonists are actively being investigated in the clinic in a variety of tumors, alone or in combination with immune checkpoint blockade or cancer vaccines." (PMID 27852037, 2016). "In this paradigm, the generally pro-inflammatory cancer microenvironment leads to IDO1/TDO2 over-expression in stoma (epithelial and endothelial cells) and/or antigen-presenting cells (APCs) such as dendritic cells (DC) resulting in depletion of tryptophan in the local milieu." (PMID 26646699, 2016). "Since the discovery of the essential role played by IDO1 in mediating maternal foetal tolerance, a great deal of interest has focused on the roles that IDO1 and other KP enzymes may play in cancer immunology." (PMID 26646699, 2016). "Finally, the results of our study have implications for the treatment of not only HIV but also other diseases in which IDO1 and the KP are thought to play a role, such as cancer." (PMID 28066416, 2016). "Our results indicate that an IDO1-mediated immunosuppressive mechanism is involved in weakening the antitumor efficacy elicited by AML-loaded DCs and that specific inhibition of IDO1 might be required for development of cancer vaccines." (PMID 25815345, 2015). "These factors help to explain why L-1MT is considered a poor physiological inhibitor of IDO in comparison to D-1MT and why D-1MT has broader clinical uses against cancers that overexpress any tryptophan catabolic enzyme, such as IDO1, IDO2 and tryptophan-2,3-dioxygenase (TDO)." (PMID 26674411, 2015). "The IDO1–AhR axis has been described in several settings of immune tolerance, including maternal–fetal tolerance, immune suppression induced by several human cancers, and endotoxin tolerance." (PMID 25360135, 2014). "Besides finding the right combination partner, a future challenge will certainly be the identification of cancer types and patients who will benefit from an IDO1 inhibitory approach." (PMID 25628622, 2014). "In addition to identifying novel TDO inhibiting compounds, it is logical to test – based on the experiences with IDO1 – existing anti-cancer compounds for their potential to inhibit TDO." (PMID 25628622, 2014). "Conceptually and also supported by preclinical studies, IDO1 inhibition may enhance the efficacy of active cancer vaccines as it may break cancer-induced tolerance." (PMID 25628622, 2014). "IDO1 is now firmly established target of drug discovery in cancer immunotherapy." (PMID 25628622, 2014). "However, it has been shown that the 1-d-MT isomer upregulates IDO1 in human cancer cells in vitro, and this upregulation can circumvent the enzymatic inhibitory effect of 1-MT." (PMID 24911872, 2014). "Moreover, an autocrine signaling loop involving IL-6, STAT3, and AhR was found to sustain the constitutive expression of IDO1 in human cancer cells." (PMID 25360135, 2014). "Studies also suggest that IDO-1 expression correlates with and may be a significant predictor of poor clinical prognosis in patients with various cancers." (PMID 25415278, 2014).